KRAS (KRas proto-oncogene, GTPase)
Diseases named in the same sentence as KRAS in open-access papers (continued):
Sharing a sentence is not in itself a finding about the gene and the disease.
cancer (continued). "Hepassocin (HPS/FGL1) is involved in regulating lipid metabolism and the progression of several cancer types; however, the underlying mechanism of HPS/FGL1 in the KRAS mutant PDAC cells undergoing eicosapentaenoic acid (EPA) treatment remains unclear." (PMID 33801246, 2021). "Cancer genome sequencing efforts reveal that in addition to mutations in growth-promoting signaling pathways such as in EGFR and KRAS, chromatin-modifying enzymes and epigenetic regulators such as KMT2D, ARID1A, and TET2 are also frequent targets of genetic alterations." (PMID 34236315, 2021). "Furthermore, we found that PGK1 displayed correlations to hallmarks of cancer including glycolysis, mTORC1 signaling, hypoxia, Hedgehog signaling, Wnt β-catenin signaling, myogenesis, and KRAS signaling." (PMID 34790279, 2021). "Therefore, SW480 was selected as the model for our study aiming to investigate the link between KRAS activities and the regulation of exosomes in cancers." (PMID 33466836, 2021). "Thus, the data indicate that LKB1 loss induces DNA hypermethylation, thereby controlling ALKBH5 expression in KRAS mutant cancer cells." (PMID 34016959, 2021). "However, several previous and ongoing attempts to target KRAS-driven cancers have showed encouraging results but with high incidents of partial response, indicating that modulation of oncogenic KRAS signals is more complex than expected." (PMID 33672357, 2021). "Notably, KRAS mutant cancer cells have been shown to develop anticancer drug resistance through hyperactivation of mTOR signaling." (PMID 34003553, 2021). "Since minimal/no growth inhibition effect was observed in EGFR, KRAS-mutated cancer cells in vitro, to confirm the specific inhibiting activity against these oncogenic driver genes, we generated each EGFR and KRAS overexpressed NIH3T3 cells and gilteritinib was treated in vivo." (PMID 33627640, 2021). "Among the three MAP kinases, Raf kinases are the most critical effectors in KRAS-driven cancers." (PMID 34946644, 2021). "On the other hand, the evaluation of genes involved in the RAS signaling pathway (including the NRAS, HRAS and KRAS genes), a pathway involved in several cancer types, did not reveal any variant in our cohort." (PMID 34284772, 2021). "In mice, the deletion of KRAS has been found to be more lethal than the deletion of NRAS and HRAS; therefore, the use of mutant allele-specific inhibitors in humans was proposed to be a more targeted, viable approach for treating RAS mutant cancers." (PMID 34830283, 2021). "Most patients with KRAS-mutant cancers also have high cyclin D1 expression." (PMID 34830174, 2021). "Moreover, it is well known that mTOR is upregulated in KRAS mutant cancers, but KRAS can directly turn on the self-digestive process, keeping the autophagy active." (PMID 33925206, 2021). "Corresponding to our system biological analysis, this combined pharmacologic ascorbate and chloroquine treatment in KRAS mutant cancers might be a therapeutic approach in anti-cancer therapies." (PMID 33925206, 2021). "Additionally, BI-3406 is a potent and selective SOS1-KRAS interaction inhibitor that reduces RAS-GTP levels and curtails MAPK pathway signaling in KRAS-driven cancers." (PMID 33917906, 2021). "Although some KRAS-associated genes were found to regulate cancer cell metabolism, the mechanism still remained to be clarified and there was no comprehensive analysis to explore KRAS-associated metabolic signature or risk model for PC." (PMID 34660806, 2021). "For decades, KRAS oncoprotein was classified as undruggable cancer target." (PMID 34298594, 2021).
cancer (continued). "In addition, studies from our group showed that oncogenic KRAS promotes secretion of IL-1β through the MEK-ERK cascade, leading to activation and migration of cancer-associated fibroblasts (CAFs)." (PMID 34771644, 2021). "Finally, one of the Holy Grails of cancer therapy has been the development of direct and effective pharmacological inhibitors of KRAS oncoproteins." (PMID 34298710, 2021). "In this section, we highlight some of these drugs and their application for KRAS-mutant cancers." (PMID 34607583, 2021). "We provide physical evidence for a differential effect of proton radiation targeting DNA replication stress in cancer cells driven by the KRAS oncogene, which may yield a novel therapeutic opportunity." (PMID 33574444, 2021). "To test the long‐term (10 days) effects of the AMG510 and IN10018 drug combination, we performed cell colony formation assays with diverse KRAS mutant cancer, using specific doses of each combination therapy agent (based on individually testing AMG510 and IN10018 for each cell line)." (PMID 34151545, 2021). "Additionally, the sensitivity to AOA treatment has been described as a hallmark of mutant KRAS in cancer cells, which cooperates with MYC in cancer metabolic reprogramming." (PMID 34503295, 2021). "Moreover, in some cases, combined inhibition of oncogenic signaling plus autophagy has been shown to be an effective strategy for the treatment of cancers driven by oncogenic KRAS or BRAF both in preclinical models and in clinical trials." (PMID 34298710, 2021). "Comparing these data with G12D mutation may reveal context-specific combination therapies, which could be the next generation treatment of KRAS mutant cancers that are notorious for its heterogeneity." (PMID 33137185, 2021). "PI3K pathway inhibitors are more suitable as an option in combination therapy for KRAS-mutant cancers, because there are overlapping feedback mechanisms between the MAPK and PI3K pathways, meaning that inhibition of one pathway can result in the compensatory activation of the other." (PMID 34742312, 2021). "Moreover, PD-L1 expression was also suppressed in cancer cells, indicating that STK11-deficient KRAS mutations lead to anti-PD-1/PD-L1 resistance in cancer cells." (PMID 35070984, 2021). "However, epitopes with weak binding to HLA are generally more challenging to express, including clinically significant cancer epitopes such as KRAS G12D." (PMID 34584159, 2021). "Targeting the KRAS pathway for cancer therapy has been particularly challenging, in spite of the vast amount of knowledge accumulated on the genetic alterations leading to pathway activation in tumors, and on the signaling networks that are driven by activated RAS oncoproteins." (PMID 34257283, 2021). "Forty years after the discovery of KRAS as a transforming oncogene, we are on the verge of approval of the first KRAS-targeted drug combinations, thus therapeutically unifying Paul Ehrlich’s century-old “magic bullet” vision with Rudolf Virchow’s cancer inflammation theory." (PMID 33809660, 2021). "Previous studies have shown that lung carcinogenesis is attributed to the gain-functional mutation of several cancer-associated genes, including the epidermal growth factor receptor (EGFR), Kirsten rat sarcoma viral oncogene homolog (KRAS), and v-raf murine sarcoma viral oncogene homolog B1 (BRAF)." (PMID 34422661, 2021).
cancer (continued). "In addition, some cancer types, such as RB1-deficient breast cancers, KRAS-driven cancers, and chemoresistant melanoma, are particularly reliant on OXPHOS activity and are especially sensitive to OXPHOS inhibition." (PMID 34827664, 2021). "Further, our data from experiments with multiple primary KRAS G12C inhibition‐resistant cancer models showed elevated YAP activity upon AMG510 treatment and significant reductions in the extent of YAP activation upon the combination treatment (AMG510 and IN10018)." (PMID 34151545, 2021). "Toward this, we created a new Drosophila cancer model in which downregulation of Rbf1 is combined with downregulation of Pten and overexpression of Ras (Drosophila Ras85D is a single high-scoring ortholog of human KRAS, HRAS, and NRAS)." (PMID 33591981, 2021). "This would imply that incident cancers may develop from other, KRAS wild-type lesions that are more difficult to detect." (PMID 34206061, 2021). "“MYC”, “BMI1”, “MEL18”, and “KRAS” collections played oncogenic roles in cancer course." (PMID 34094897, 2021). "Although mTOR (mammalian target of rapamycin), a well-known inhibitor of autophagy-dependent survival in physiological conditions, is also activated in KRAS mutants, many recent studies have revealed that autophagy becomes hyper-active in KRAS mutant cancer cells." (PMID 33925206, 2021). "Cancers harboring RAS mutations have remained genomically untargetable more than 30 years after the initial discovery of the oncogene, and attempts to target KRAS directly or through downstream mechanisms have been met with limited efficacy in clinical trials." (PMID 34845311, 2021). "In addition, UR analysis indicated the upregulation of ERK signaling by p-eIF2α, which plays a major role in KRAS-driven cancer growth." (PMID 34330898, 2021). "Thus, although RAS (KRAS, NRAS, HRAS) is mutated in ∼25% of all cancers, treatment of these patients is challenging." (PMID 33130216, 2021). "KRAS and BRAF are common sites of somatic mutations in many types of human cancers, especially CRC." (PMID 31859449, 2020). "The currently available studies suggest that solving the outstanding issues regarding KRAS could lead to development of effective drugs that have a significant impact on cancer treatment." (PMID 32486141, 2020). "REM sleep loss also affected several genes such as prostaglandin-endoperoxide synthase (Ptgs2), B-cell lymphoma 2 (Bcl-2), Proto-Oncogene, Tyrosine Kinase receptor (Kit), KRAS Proto-Oncogene (K-Ras), and Fos Proto-Oncogene (Fos), which are marked in cancer pathways." (PMID 33114225, 2020). "KRAS (p.G12C) is found mutated in all samples except A2, while KRAS p.G12D is found in A1 and A2 but not in cancer (Panel Seq)." (PMID 32895052, 2020). "However, it was also reported that a HDAC inhibitor, romidepsin, preferentially induces apoptosis in cancer cells harboring mutant KRAS." (PMID 32947833, 2020). "In this review, we attempt to summarize the multiple layers how calmodulin can regulate KRas and Rac1 GTPases in a variety of cellular events, with biological consequences and potential for therapeutic opportunities in disease settings, such as cancer." (PMID 32456244, 2020). "KRAS was a pivotal regulator in the glycolysis of cancer cells." (PMID 33005174, 2020).
cancer (continued). "Therefore, our tool helped us to put the light on new regulations of KRAS activation during cancer initiation." (PMID 32887255, 2020). "Hotspots, recurrently mutated DNA positions in cancer, are thought to be oncogenic drivers because random chance is unlikely and the knowledge of clear examples of oncogenic hotspots in genes like BRAF, IDH1, KRAS and NRAS among many other genes." (PMID 32386297, 2020). "In addition, studies using the proof-of-concept small molecule inhibitors of ICMT confirmed its role in regulating TAZ and self-renewal, demonstrating the potential utility of targeting ICMT to control aggressive KRAS-driven cancers." (PMID 32561852, 2020). "Genetically, type I cancers are characterized by minor chromosomal instability and may harbor BRAF, KRAS and PTEN mutations." (PMID 33036656, 2020). "Interestingly, G12D, which is the most frequent KRAS mutant in cancer, appears most similar in its dynamics compared to WT." (PMID 31988705, 2020). "We constructed an SH based nomogram with good discrimination and calibration which might help the clinicians to predict the 1-year, 2-year and 3-year cancer specific death of CRC patients who had KRAS testing." (PMID 32547859, 2020). "There is evidence that even major and/or cancer-initiating driver mutations (e.g. APC, IDH1/2, KRAS, PIK3CA, etc.)are differentially selected depending on cancer type, strongly suggesting a role for the TME, broadly defined, in selecting many of the common driver mutations." (PMID 32289242, 2020). "Similar result was also observed following CDC6 depletion in KRAS positive cancer cells." (PMID 32854236, 2020). "For instance, there are no structures available for the KRAS mutants G12S (7% of all KRAS G12X mutations observed in cancer), G13C (6% of all KRAS G13X mutations), Q61R and Q61K (19% and 8% of all KRAS Q61X mutations, respectively) (COSMIC v.90)." (PMID 31988705, 2020). "Consequently, the reduction of GTP binding affinity of KRAS mutants by H-REV107 peptide in cancer cells influenced cell proliferation by inhibiting the RAS signaling pathway and inducing apoptosis." (PMID 32486141, 2020). "The Kirsten rat sarcoma (KRAS) is a crucial gene in the development of a variety of cancers." (PMID 33114622, 2020). "As these compounds can potentially identify mutant KRAS in different cancer types, they may have potential for development as a diagnostic imaging approach for stratification of patients to different treatment groups." (PMID 33169204, 2020). "In summary, the data show a vulnerability of KRAS-mutant cells towards suppression of MCM7 and suggest that inhibiting DNA replication licensing might be a viable strategy to target KRAS-mutant cancers." (PMID 32612138, 2020). "To illustrate, MSI positive stage II and III patients with double wild-type cancers had a 5-year cancer-specific survival of 93% (95% CI 84–100%); while, patients with cancers harboring mutations in either BRAF or KRAS had a 5-year cancer-specific survival of 76% (95% CI 67–85%)." (PMID 32458162, 2020). "Interestingly, a relation between deregulation of mitochondrial functions and KRAS mutations and RAS direct interaction with the mitochondrial outer-membrane following PKC phosphorylation in cancers were already reported." (PMID 33187149, 2020). "Thus, increased Circ-MEMO1 ultimately results in higher levels of KRAS, promoting cancer cell proliferation and survival." (PMID 33172038, 2020). "Notably, although KRAS mutations are some of the most frequent genetic mutations in human cancers 3, particularly in CRC, the dysregulated miRNAs and their functions and underlying mechanisms following KRAS mutation have yet to be fully explored." (PMID 32641995, 2020). "Effective anti-KRAS therapies for cancer are now being developed for clinical use." (PMID 33244099, 2020). "It is tempting to speculate that the inhibitors are less effective in KRAS mutant cancers due to their increased resistance." (PMID 32612138, 2020).
cancer (continued). "With the presented computer‐aided approach coupled with a stepwise experimental validation, we have reported here the design of a novel chemical series binding to KRASG12C with high potential for the development of pioneering KRAS‐targeted anti‐cancer treatments." (PMID 32237114, 2020). "In three patients (9.375%) with primary cancer positivity, no mutation of the KRAS oncogene was observed in the metastasis, the opposite in one patient (7.69%)." (PMID 32867151, 2020). "For example, in KRAS-driven cancers, calmodulin binds KRAS, and can directly activate PI3K and AKT." (PMID 32325894, 2020). "KRAS mutations were also shown to be functionally involved in the downregulation of major histocompatibility complex (MHC) class I molecules, thereby causing the reduced ability of CD8+ cytotoxic T cells to recognise cancer cells." (PMID 33116132, 2020). "Indeed, research has shown that KRAS mutant cancer cells are highly sensitive to PLK1 inhibition, wherein cancer cells carrying the oncogenic mutation KRAS were sensitive to PLK1 depletion by shRNA or to treatment with PLK1 inhibitors." (PMID 32486290, 2020). "Thus far, directly targeting oncogenic KRAS only succeeded in one certain form, KRASG12C, which comprises only 12% of KRAS mutations in all human cancers, so it is still needed to develop new target molecules for other oncogenic KRAS." (PMID 33122197, 2020). "Thus, the network diversity value of it (G12V, network diversity = 0.40) is relatively high than KRAS G12R (network diversity = 0.28), representing a different cancer specificity." (PMID 31925297, 2020). "Mutations within the Ras family are not evently distributed, with KRas mutations found in 85% of these cancers, followed by NRas (11%) and HRas (4%)." (PMID 32456244, 2020). "Although KRAS is the most frequently mutated oncogene in human cancers, no therapeutic agent directly targeting RAS has yet been approved." (PMID 32813918, 2020). "DHODH suppression has been reported to confer a metabolic vulnerability in KRAS-driven cancers." (PMID 32824193, 2020). "KRAS-G12C, one of the three most frequent mutations caused in cancer and as it is a non-native cysteine, therefore it can be selectively targeted." (PMID 32770300, 2020). "Among the five cases of KRAS discordance, three showed KRAS mutations in cancer gene panel testing but not in KRAS mutation analysis and two showed KRAS mutations in KRAS mutation analysis but not in cancer gene panel testing." (PMID 31999789, 2020). "A number of genetic markers such as NRAS, KRAS, and BRAF are used in cancer risk stratification." (PMID 33328538, 2020). "Therefore, studying the prenylation rates of KRAS in vivo is of particular interest in the cancer field." (PMID 32887255, 2020). "In summary, investigating the potential of targeting KRAS signalling and its induced effects in cancer opens up new perspectives for combination approaches, whether with standard therapy, immunotherapy or targeted agents." (PMID 33116132, 2020). "Since the combination of FMD/STS and vitamin C increased ROS levels in KRAS-mutant cancer cells, we investigated whether this correlates with an increased pool of labile ferrous iron." (PMID 32393788, 2020). "Moreover, dimeric PKM2 is maintained by tyrosine phosphorylation, and other post-translational modifications, all of which tend to be upregulated in cancer cells due to overexpression of growth factor receptors and mutant KRas." (PMID 31819190, 2020).